CNR1 (cannabinoid receptor 1)
Diseases named in the same sentence as CNR1 in open-access papers (continued):
Sharing a sentence is not in itself a finding about the gene and the disease.
Anxiety (continued). "It would be interesting to explore whether migraine, anxiety and sleep disorders in patients with rare deleterious variants in CNR1 could be alleviated by treatment with CB1 agonists that could effectively stimulate the impaired and/or remaining functional CB1 receptors." (PMID 29145497, 2017). "Chronic stress gives rise to hypermethylation of the CNR1 promoter, leading to decreased levels of CB1R expressed in brain areas involved in emotion and stress resilience, effects contributing to anxiety and depression." (PMID 41303613, 2025). "Cannabinoid receptor 1 type (CB1R) is abundant in the central nervous system, especially in the cortex and hippocampus, and mice with full CB1R deletion exhibit more pronounced anxiety-like behavior." (PMID 38685914, 2024). "For instance, specific genetic variations in the CNR1 (gene coding the Cannabinoid type 1 Receptor, CB1) rs7766029 polymorphism have been associated with the development of depression and anxiety." (PMID 40656087, 2024). "Taken together, the data seem to suggest that the invalidation of the Cnr1 gene increases anxiety conditionally, and the condition to this effect is the aversiveness of the testing environment." (PMID 37958761, 2023). "Increased mRNA levels of Cnr1 in the PFC of both KO and WT were associated with reduced anxiety behavior, as indicated by more time spent in the light compartment of the LDT (r = 0.54, p < 0.0001)." (PMID 37149657, 2023). "Many of the behavioral phenotypes of Cnr1-/- mice, including increased anxiety and maternal care deficits, are also observed in mice deficient for DAGLa, the main enzyme responsible for 2-AG production in the CNS." (PMID 32997200, 2021). "Further, control and stressed Cnr1−/− mice spent significantly less time in the centre than corresponding Cnr1+/+ mice, indicating increased baseline anxiety-like behaviour." (PMID 33723234, 2021). "Deletion of CNR1 gene in mice (CB1−/− mice) has been another important tool to elucidate the role of this cannabinoid receptor in anxiety." (PMID 32395111, 2020). "In the present study we investigated the interaction of GABRA6 rs3219151 and CNR1 rs7766029 in interaction with different types of recent life events on the presence of depression and anxiety in a large general population sample." (PMID 31024264, 2019). "Specifically, in case of anxiety CNR1 rs7766029 showed an interaction with recent financial stress and GABRA6 rs3219151 with recent social network-related stressors." (PMID 31024264, 2019). "For this reason, we chose to evaluate Dagla and Cnr1 KO mice in a series of tests designed to evaluate anxiety, depression, and other behaviors." (PMID 26082754, 2015). "With respect to anxiety, the only study that has been done with the CNR1 gene is one that identified an epistatic relation between CNR1 and the serotonin transporter." (PMID 24286185, 2013). "In particular, polymorphisms in the CB1R gene (CNR1) are associated with anhedonia in individuals exposed to childhood abuse and could interact with other genes to contribute to anxiety phenotypes." (PMID 35105857, 2022). "In addition, a clinical phase I/II trial with SR14716A (rimonabant), a CNR1 antagonist agonist showed that it produced serious adverse neuropsychiatric events such as anxiety, depression, and even suicidal ideation." (PMID 36138887, 2022). "Interactions of number of recent negative life events and CNR1 (rs7766029) or GABRA6 (rs3219151) polymorphisms on BSI anxiety and BSI depression scores as the outcome in the combined Budapest + Manchester sample." (PMID 31024264, 2019). "Thus this is the first study to report that CNR1 rs7766029 selectively mediates the effects of financial stress, but not other types of recent life events in both depression and anxiety symptoms." (PMID 31024264, 2019).
Anxiety (continued). "In line with our previous study of 5-HTTLPR, the present results of CNR1 rs7766029 support a distinct role of financial stress among different life events in the development of depression and anxiety symptoms possibly related to the prominent and pervasive impact of this type of stress." (PMID 31024264, 2019). "This suggests that the observed reduction in Cnr1 expression demonstrated here may contribute to our observation of anxiety-like behaviour following PAE." (PMID 23915435, 2013). "Previous studies evaluating Cnr1 knockout mice have demonstrated increased anxiety-like phenotypes." (PMID 23915435, 2013). "In rodents, deleterious effects of adolescent exposure with cannabinoid receptor 1 agonists have been reported in adult behavior (see review), and THC administration affects long-term memory and increases anxiety states." (PMID 33807989, 2021). "In our study we demonstrated that genetic variation in two distinct neurochemical systems, namely, rs7766029 in the CNR1 and rs3219151 in GABRA6, mediate the effects of different types of recent stress in depression or anxiety." (PMID 31024264, 2019). "The number of STR repeats in the CNR1 gene in correlation with anxiety and openness to experience in the control group does not mean that the STR repeats are strongly influencing these traits." (PMID 38791212, 2024). "Our hypothesis suggests that a higher number of AAT repeats in the 3′ region of the CNR1 gene may lead to lower availability of the CB1 receptor for AEA and 2AG, which in turn contributes to the occurrence of anxiety." (PMID 38791212, 2024). "The cannabinoid receptor 1 (CB1) is the most abundantly expressed GPCR in the brain and it is a therapeutically useful target involved in a wide variety of physiological processes such as: metabolic regulation, craving, pain, and anxiety)." (PMID 36304142, 2022). "The results suggested that CNR1 rs7766029 interacted significantly with financial but not with other types of life events to increase the vulnerability to develop depression and anxiety." (PMID 32395111, 2020). "Results indicated that CNR1 rs7766029 interacted significantly with financial but not other types of life events both in case of depression and anxiety symptoms." (PMID 31024264, 2019). "Beyond CNR1, eCB system could exert actions on other targets including CNR2, transient receptor potential vanilloid receptor type 1 (TRPV1), or cyclooxygenase-2 (COX2) to participate in improvement of anxiety." (PMID 33178009, 2020). "Furthermore, previous associations between variation in CNR1 and FAAH and fear extinction have been observed in response to short‐term experimentally conditioned fears in adults and not to clinical levels of anxiety in children and adolescents." (PMID 27346075, 2017). "Mice that are experimentally manipulated to harbor a non-functional CNR1 gene (CB1 knockout), or that are treated with CB1 antagonists, display behaviors that suggest impacts related to pain sensitivity, anxiety, memory and sleep, amongst others." (PMID 29145497, 2017).
depression (147 papers, 2007 to 2026). "Nevertheless, the neurobiological mechanisms of the potential role of CB1R and CNR1 gene polymorphisms in PD-related depression remain to be explored." (PMID 37374342, 2023). "Several experimental examinations in humans reveal a significant association between the functional (AAT)n-polymorphism within the CNR1 gene and depression by patients with Parkinson’s disease." (PMID 36932421, 2023). "Genotyping of the 5‐HT1A, 5‐HT2A, and CNR1 polymorphism in patients with depression and healthy participants." (PMID 37984468, 2023). "Several studies have reported associations between genetic variations in the CB1 receptor (CNR1) and susceptibility to developing depression (see review Bright & Akirav, 2022)." (PMID 37984468, 2023). "In summary, our results suggest an altered endocannabinoid system in patients with a depressive disorder and a possible influence of the polymorphism in the CNR1, 5‐HT1A, and 5‐HT2A genes." (PMID 37984468, 2023). "Patients who developed a depressive disorder showed higher frequencies of the mutated gene in the CNR1 gene." (PMID 37984468, 2023). "The results showed a potential role of the CNR1 rs806367 polymorphism in susceptibility to treatment-resistant depression (TRD)." (PMID 35563156, 2022). "Single nucleotide polymorphisms in the CNR1 gene were associated with depression and other mood disorders." (PMID 36430254, 2022). "On the other hand, the presence of 2 long alleles of the polymorphic triplet (AAT)n of CNR1 gene was associated with reduced prevalence of depression in Parkinson's disease patients." (PMID 32395111, 2020). "Certain polymorphisms in the CB1R coding gene—CNR1—seem to be associated with susceptibility to depression and its treatment-resistance development." (PMID 32545780, 2020). "CNR1 variation increases risk and vulnerability to depression upon exposure to both early and recent stress." (PMID 31024264, 2019). "CNR1 polymorphisms were found to be associated with substance use disorders, depression, anxiety disorders, eating disorders, schizophrenia, and attention deficit hyperactivity disorder." (PMID 26131011, 2015). "Taken together, these studies would suggest that the A allele in the rs1049353 polymorphism of the CNR1 gene results in some level of protection against the development of depression, particularly in response to stress exposure." (PMID 24286185, 2013). "With respect to the CB1 receptor (CNR1 gene), several studies to date have examined different polymorphisms in the CNR1 gene and how they relate to psychiatric illness, particularly depression." (PMID 24286185, 2013). "Furthermore, a single nucleotide polymorphism in CNR1 is not only associated with depression but also interferes in treatment." (PMID 39796008, 2024). "CNR1-deficient mice can also be used to model depression in mice." (PMID 37108261, 2023). "Furthermore, depression in human patients has been linked with several polymorphisms in the CNR1 gene." (PMID 33401515, 2021). "Furthermore, several CNR1 polymorphisms appeared to be related with high neuroticism and low agreeableness personality traits, increasing the risk to develop depression." (PMID 32395111, 2020). "It is, however, assumed that a changed CNR1 expression plays an important role for the pathogenesis of depression." (PMID 36932421, 2023). "In this study, we examined the association among 5‐HT1A (rs6295), 5‐HT2A (rs6311), and CNR1 (rs1049353) and measured the concentration of AEA and 2‐AG in patients with depression compared to healthy controls." (PMID 37984468, 2023). "Subsequently, we demonstrated that sE2 induced the pro-inflammatory phenotype of microglia through ERα/NF-κB signaling pathway and downregulated the expression of cannabinoid receptor 1 in neuronal cells, which were important in the pathogenesis of depression." (PMID 37679787, 2023).
depression (continued). "The possible effects of the polymorphism in the genes of the CNR1 (rs1040353), 5‐HT1A (rs6295), and 5‐HT2A (rs6311), which are already related to depression, were investigated in this study." (PMID 37984468, 2023). "In this context, the CNR1 SNPs rs6454674 and rs806367 have been indicated to increase vulnerability to major depressive disorder and resistance to antidepressant treatment." (PMID 37374342, 2023). "The present study showed an altered endocannabinoid system and the genetic variations of the 5‐HT1A, 5‐HT2A, and CNR1 genes in patients with a depressive disorder compared to healthy participants." (PMID 37984468, 2023). "In this study, 161 patients with a depressive disorder and 161 healthy participants were examined for the distribution of the CNR1 rs4940353, 5‐HT2A rs6311, and 5‐HT1A rs6295 by high‐resolution melting genotyping." (PMID 37984468, 2023). "Then SHIV-infected rhesus monkeys were used to investigate the possible involvement of the NUCB1 and the CNR1 protein in depression-like behavior." (PMID 36138887, 2022). "A recent study analyzed the plasma concentrations of 2-AG and AEA and the CNR1, FAAH, and MGLL polymorphisms as predictors of depression severity six months after suffering a traumatic injury." (PMID 35563156, 2022). "The interaction between specific genetic variations in CNR1 and the vulnerability to depression has recently gained great interest." (PMID 35628337, 2022). "A relationship between genetic variants in cannabinoid receptor type 1 and type 2 genes (CNR; CNR1 and CNR2) and susceptibility to depression was also reported." (PMID 36430254, 2022). "Several studies have reported associations between genetic variants of the cannabinoid receptor type 1 and type 2 genes (CNRs; CNR1 and CNR2) and a susceptibility to develop depression." (PMID 35628337, 2022). "Another piece of evidence against the relationship between depression and CNR1 is a recent meta-analysis, which assessed the relation between CNR1 and CNR2 polymorphisms and depressive disorder susceptibility." (PMID 35628337, 2022). "We then examined the relationship between CNR1 expression and diagnosis in neurotypical adult controls, and schizophrenia, bipolar, and major depression samples (age > 13)." (PMID 32433545, 2020). "By integrating data from the literature, we revealed 4 genes of interest (GNB3, CNR1, MTHFR, and NCAM1) that were likely to be associated with the aetiology of both MI and depression." (PMID 31185929, 2019). "In conclusion, using literature mining methods, the GNB3, CNR1, MTHFR, and NCAM1 genes were identified and directly or indirectly implicated in the regulation of MI and depression." (PMID 31185929, 2019). "In case of depression, CNR1 rs7766029 similarly interacted with recent financial stress, GABRA6 rs3219151, however, interacted with recent illness and personal problem stressors." (PMID 31024264, 2019). "Accordingly, the AAT triplet repeat polymorphism of the CNR1 gene, and different single nucleotide polymorphism (SNPs) of CNR1 and FAAH genes have been associated with depressive symptoms and with major depression." (PMID 30515077, 2018). "The effect of variation within the CNR1 gene for depression have been shown." (PMID 36932421, 2023). "CNR1, an important component of the endocannabinoid system, plays an important role in depression." (PMID 37108261, 2023). "As several polymorphisms are known to increase the likelihood of developing depression, we analyzed the genotypes of the 5‐HT1A (rs6295), 5‐HT2A (rs6311), and the CNR1 (rs1049353) genes to explore a possible link between alterations in these genes and depression." (PMID 37984468, 2023). "Expressions of both nucleobindin 1 (NUCB1) and cannabinoid receptor 1 (CNR1) in the neurons have been found to alter in patients with depressive disorder, but whether it is involved in the development of depression in the context of HIV infection is unknown." (PMID 36138887, 2022).
depression (continued). "We speculate that decreased CNR1 expression by SHIVKU-1 infection results in depressive disorder because there is support for existing cannabinoid signaling pathways that can decrease neuronal injury." (PMID 36138887, 2022). "Both CNR1 and FAAH gene polymorphisms might also contribute to susceptibility to bipolar disorder and major depression." (PMID 30279403, 2018). "In particular, in patients with major depression, CNR1 SNPs may affect responsiveness of subcortical structures, including the amygdala and striatum, to social rewarding stimuli." (PMID 30515077, 2018). "Finally, genetic variability in the CNR1 gene seems to be involved in the etiology of major depression and in the clinical response to the selective serotonin reuptake inhibitor citalopram." (PMID 30279403, 2018). "Furthermore, associations have been found between gene polymorphisms in CNR1, CNR2 (genes coding for CB1R and CB2R, respectively) and FAAH genes and behaviours characteristic of depression." (PMID 26483037, 2016). "However, a recent meta-analysis did not reveal an association between CNR1 rs1049353 or AAT repeat polymorphism with depression risk." (PMID 37374342, 2023). "Some studies could show a link between the CNR1 rs1049353 polymorphism and depression, and others not." (PMID 37984468, 2023). "Besides the endocannabinoid receptor polymorphism CNR1 rs1049353, the polymorphism 5‐HT1A rs6295 and 5‐HT2A rs6311 could play a crucial role in the etiology of depression." (PMID 37984468, 2023). "A recent meta-analysis indicated that CNR1 rs1049353 or AAT triplet repeat sequence polymorphisms were not relevant for depression susceptibility, but CNR2 rs2501432 gene polymorphisms may be strongly correlated with depression." (PMID 36430254, 2022). "However, two other studies found no relation between CNR1 microsatellite polymorphisms and depressive disorders or between CNR1rs1049353 and MDD." (PMID 35628337, 2022). "In major depression, SNPs of the CNR1 may also influence the response to antidepressant treatment." (PMID 30515077, 2018). "The expression level of the 5-HT1A, DRD1, ADRA-2A, GABA-A α1, CNR1, NR3C2, NOD1, NLRP3 and MC4R; BDNF levels, glial activity and intestinal permeability were determined in chronic stress-induced depression in rats." (PMID 40281288, 2025). "On the other hand, the existence of at least one short CNR1 gene allele carrying less than 16 AAT repeats was correlated with a higher frequency of depression among PD patients in this study, suggesting that ECS may be majorly implicated in the pathophysiology of PD depression." (PMID 37374342, 2023). "Herein, down-regulation of CNR1 expression and up-regulation of NUCB1 expression in neurons were found in the co-occurrence of depression disorder and SHIV infection, as detected by IHC and Western blot." (PMID 36138887, 2022). "Moreover, it has been evidenced that CNR1 SNPs may interact with previous negative experiences increasing the susceptibility to depression." (PMID 30515077, 2018). "Selective dysregulation of the peripheral ECS was observed in SZ, marked by reduced DNA methylation at the CNR1 gene promoter that encodes CB1R in peripheral blood mononuclear cells (PBMCs), a change not seen in bipolar or major depressive disorder." (PMID 40766927, 2025). "Regarding the polymorphism in the CNR1 gene, not many studies have investigated the distribution of the CNR1 rs1049353 in patients with depression." (PMID 37984468, 2023). "The authors suggested that patients with FM without depression and those with FM and depression show a significant difference in the genotypic distribution related to SNP rs6454674 in the cannabinoid receptor 1 gene (CNR1)." (PMID 36360283, 2022). "GNB3, CNR1, MTHFR, and NCAM1 are putative new candidate genes that may influence the interactions between MI and depression, and may represent potential targets for therapeutic intervention." (PMID 31185929, 2019).
depression (continued). "Taken together, these results suggest that the overexpression of the GNB3, CNR1, MTHFR, and NCAM1 genes may contribute to the development of MI and depression and may play a role in the interaction between these two diseases." (PMID 31185929, 2019). "Specifically, in our study, high CNR1 expression in the brain areas was observed at the nucleus accumbens, which has been suggested to be related to a lack of interest and other symptoms of depression." (PMID 31185929, 2019). "Based on genotyping, no different distributions of the CNR1, 5‐Ht1A, and 5‐HT2A genes were found in patients with depressive disorder and healthy participants." (PMID 37984468, 2023).